LILRA2 (leukocyte immunoglobulin like receptor A2)
Description:
Part of the innate immune responses against microbial infection. Specifically recognizes a set of N-terminally truncated immunoglobulins that are produced via cleavage by proteases from a range of pathogenic bacteria and fungi, including L.pneumophila, M.hyorhinis, S.pneumoniae, S.aureus and C.albicans. Recognizes epitopes that are in part in the variable region of the immunoglobulin light chains, but requires also the constant region for signaling. Binds to a subset of cleaved IgM, IgG3 and IgG4 molecules, but does not bind cleaved IgA1. Binding of N-terminally truncated immunoglobulins mediates activation of neutrophils. In monocytes, activation leads to the release of CSF2, CF3, IL6, CXCL8 and CCL3 and down-regulates responses to bacterial lipopolysaccharide (LPS), possibly via down-regulation of TLR4 expression and reduced signaling via TLR4. In eosinophils, activation by ligand binding leads to the release of RNASE2, IL4 and leukotriene C4. Does not bind class I MHC antigens.
Synonyms: LIR-7; CD85h; ILT1; LIR7
Tractability: Small molecule: it has a high-quality binding pocket. Antibody: UniProt places it where antibodies can reach, with high confidence; its Gene Ontology location is reachable by antibodies, with high confidence; UniProt predicts a signal peptide or a membrane-spanning region. PROTAC: its protein half-life has been measured.
Gene: Protein-coding gene on chromosome 19 (54,572,920 to 54,590,287, forward strand). Ensembl gene ENSG00000239998.
Subcellular location: Cell membrane; Secreted (Isoform 4)
Pathways (Reactome):
Immune System: Immunoregulatory interactions between a Lymphoid and a non-Lymphoid cell
Gene Ontology:
Molecular function: IgM binding; antigen binding; inhibitory MHC class I receptor activity; signaling receptor activity
Biological process: innate immune response activating cell surface receptor signaling pathway; negative regulation of lipopolysaccharide-mediated signaling pathway; negative regulation of toll-like receptor 4 signaling pathway; neutrophil activation involved in immune response; positive regulation of calcium ion transport; positive regulation of cell activation; positive regulation of granulocyte colony-stimulating factor production; positive regulation of granulocyte macrophage colony-stimulating factor production; positive regulation of interleukin-1 beta production; positive regulation of interleukin-6 production; positive regulation of interleukin-8 production; positive regulation of tumor necrosis factor production; defense response; immune response-inhibiting cell surface receptor signaling pathway; interleukin-10-mediated signaling pathway; signal transduction; cell surface receptor signaling pathway
Cellular component: plasma membrane; extracellular region
Genetic constraint (gnomAD): Loss-of-function variants: 45 observed, 45.44 expected, observed/expected ratio (o/e) 0.99, 90% interval 0.78 to 1.27. The upper end of that interval is the gene's LOEUF score, 1.27, which puts it in group 5 of 6, group 1 being the genes least tolerant of losing a copy. Missense variants: 651 observed, 565.42 expected, observed/expected ratio (o/e) 1.15, 90% interval 1.08 to 1.23. Synonymous variants: 279 observed, 234.87 expected, observed/expected ratio (o/e) 1.19, 90% interval 1.08 to 1.31.
Homologues: Orthologues: chimpanzee LILRA2 (86% identical), macaque LILRAB (65% identical), rat Pirb (50% identical), mouse Pira12 (49% identical), mouse Pira2 (49% identical), mouse Pira1 (49% identical), mouse Pira13 (49% identical), mouse Lilra6 (48% identical), mouse Pirb (48% identical), rat LOC134485274 (48% identical), rat Lilrb3 (43% identical), rat Lilrb2 (31% identical), and 3 more. Paralogues in human: LILRA1 (81% identical), LILRB1 (75% identical), LILRB2 (74% identical), LILRA6 (65% identical), LILRB3 (64% identical), LILRA4 (62% identical), LILRB5 (60% identical), LILRB4 (33% identical), LILRA5 (31% identical), KIR3DL1 (27% identical), KIR3DL2 (26% identical), KIR3DL3 (26% identical), and 13 more.
Diseases named in the same sentence as LILRA2 in open-access papers:
LILRA2 is named in the same sentence as 23 diseases in open-access papers, as found by Europe PMC text mining. Sharing a sentence is not in itself a finding about the gene and the disease. The quoted sentences say what the papers report.
leprosy (3 papers, 2017 to 2024). Leprosy is a chronic infectious disease affecting primarily the skin and peripheral nervous system. "Additionally, LILRA2 expression is significantly upregulated in lesions of patients with disseminated leprosy." (PMID 39376567, 2024). "Although the ligand for LILRA2 has not been identified, its activation inhibits TLR2/1-induced IL-12 release but maintains IL-10 release, and while the mechanism of LILRA2 activation during leprosy remains uncertain, LILRA2 is notably more highly expressed in LL than in TT lesions." (PMID 28162092, 2017).
rheumatoid arthritis (3 papers, 2013 to 2021). A chronic, systemic autoimmune disorder characterized by inflammation in the synovial membranes and articular surfaces. "Rheumatoid arthritis patients abundantly express LILRA2, LILRA3, LILRA5, and LILRB2, with the presence of LILRA2, LILRA5, and LILRB2 significantly correlating with disease activity." (PMID 34737739, 2021). "LILRA2 up-regulation is also worth mentioning as this protein induces cytokine production by monocytes while reducing their phagocytic ability and correlates with disease severity in rheumatoid arthritis." (PMID 24155895, 2013). "LILRB2, LILRB3 and LILRA2 were highly upregulated in synovial tissues from rheumatoid arthritis (RA) patients." (PMID 34594332, 2021).
Cirrhosis (1 paper, 2022). A chronic disorder of the liver in which liver tissue becomes scarred and is partially replaced by regenerative nodules and fibrotic tissue resulting in loss of liver function. "Seven DEGs (TYMP, TYROBP, CD14, TGFBI, LILRA2, GNLY, and GZMB) were common to HCC, cirrhosis, and CHB when compared to healthy controls." (PMID 35265561, 2022).
clear cell renal cell carcinoma (1 paper, 2025). "LILRA1, LILRA2, LILRA5, LILRB1, LILRB2, and LILRB3 are differentially expressed across several cancer types, including lung squamous cell carcinoma, lung adenocarcinoma, papillary renal cell carcinoma, and clear cell renal cell carcinoma, suggesting a potential pan-cancer role for LILR family genes." (PMID 40843931, 2025).
liver cancer (1 paper, 2024). An epithelial or non-epithelial malignant neoplasm that arises from the liver. "Moreover, our investigations unveiled the potential significance of the LILRA2 gene as a pivotal target for liver cancer immunotherapy." (PMID 38927691, 2024). "The expression of LILRA2 gene is lower in liver cancer patients, suggesting that the low expression of this gene in such patients may be a pivotal factor contributing to their insensitivity to chemotherapy drugs and poor response to targeted therapy." (PMID 38927691, 2024). "Moreover, through correlation analysis between prognostic risk genes and chemotherapeutic drugs, we found that low expression of LILRA2 in liver cancer patients may be an important reason for their insensitivity to chemotherapeutic drugs and poor therapeutic efficacy." (PMID 38927691, 2024). "Among these, six genes were significantly differentially expressed between liver cancer tissue and adjacent normal tissue (CSAD, SLC16A11, LILRA2, IMMP2L, GLP2R, and DHDH)." (PMID 38927691, 2024).
liver cirrhosis (1 paper, 2022). "When compared to healthy controls, only 7 DEGs, including 6 up-DEGs (TYMP, TYROBP, TGFBI, LILRA2, GNLY, and GZMB) and 1 down-DEG (CD14) were common to CHB, liver cirrhosis, and HCC." (PMID 35265561, 2022).
microscopic polyangiitis (1 paper, 2024). Microscopic polyangiitis (MPA) is an inflammatory, necrotizing, systemic vasculitis that affects predominantly small vessels (i.e. small arteries, arterioles, capillaries, venules) in multiple organs. "LILRA2 SNP rs2241524 has been reported to be associated with microscopic polyangiitis (MPA)." (PMID 39376567, 2024).
osteosarcoma (1 paper, 2025). A usually aggressive malignant bone-forming mesenchymal neoplasm, predominantly affecting adolescents and young adults. "Gene expression comparisons between groups corroborated these findings, demonstrating significantly higher expressions of CERS1, FABP3 and NPDC1 in high‐mitophagy osteosarcoma, whereas PLEKHF1 and LILRA2 were significantly less expressed." (PMID 39834330, 2025).
thyroid cancer (1 paper, 2024). "Subsequently, Bulk-seq results indicated differential expression of GFRA2 and LILRA2 genes in thyroid cancer." (PMID 39906670, 2024). "In DEG analysis, significant changes were observed in the expression of GFRA2 and LILRA2 genes in patients with thyroid cancer." (PMID 39906670, 2024). "Finally, analyses from an independent cohort at the Second Affiliated Hospital of Chongqing Medical University also demonstrated high expression of LILRA2 in thyroid cancer patients." (PMID 39906670, 2024). "However, there was a notable increase in the mRNA levels of LILRA2 in the plasma of patients with thyroid cancer, with this difference reaching statistical significance (P<0.05)." (PMID 39906670, 2024).
tuberculoid leprosy (1 paper, 2012). A principal or polar form of leprosy in which the skin lesions are few and are sharply demarcated. "In contrast, patients with tuberculoid leprosy with minimal inflammation expressed low levels of LILRA2 and demonstrated strong Th-1 responses that were effective in mycobacterial killing." (PMID 22479404, 2012).
tumor (3 papers, 2022 to 2024). "Activation of LILRA2 inhibits monocyte function and antigen presentation by dendritic cells, and high expression of LILRA2 has been associated with a poor tumor prognosis." (PMID 38799454, 2024). "Analysis of the tumour biopsies revealed that LILRA2, LILRA4, and LILRB4 were associated with the prognosis of PDAC patients." (PMID 36748687, 2023). "The result showed that PTGFR had a lower expression level in tumor tissue, yet LILRA2 and KCNA1 were highly expressed in tumor tissue." (PMID 36091124, 2022). "LILRA2, LILRA4, and LILRB4 showed low expressions in tumour tissues, in which LILRB4 was significantly lowly expressed (p < 0.001)." (PMID 36748687, 2023).
infection (1 paper, 2018). The state of being infected such as from the introduction of a foreign agent such as serum, vaccine, antigenic substance or organism. "Our analysis demonstrates that specific LILRA2+ CD64+ CD32a+ CD4+ T-cell clusters, characterized by naive and memory T-cell phenotypes, were more abundant in HIV+ patients from the early phase of infection." (PMID 29915583, 2018).
LILRA2 also shares sentences with these, for which no sentence is quoted: cancer (4 papers); breast carcinoma (2); atherosclerosis (1); bladder cancer (1); hepatitis B (1); hypospadias (1); lepromatous leprosy (1); lung adenocarcinoma (1); lung squamous cell carcinoma (1); papillary renal cell carcinoma (1); periodontitis (1).